WNK1 (WNK lysine deficient protein kinase 1)
Diseases named in the same sentence as WNK1 in open-access papers (continued):
Sharing a sentence is not in itself a finding about the gene and the disease.
colorectal cancer (5 papers, 2018 to 2026). A primary or metastatic malignant neoplasm that affects the colon or rectum. "We used the RPIA transgenic fish as a model to examine the effects of WNK1 signaling inhibitors on colorectal cancer (CRC)." (PMID 32131390, 2020). "Lastly, miR-93-5p is elevated in colorectal cancer and is known to target WNK lysine deficient protein kinase 1 (WNK1) to inhibit the invasive potential of triple-negative breast cancer cells." (PMID 29968742, 2018). "Most notably, the I-C19 treatment reduced the phosphorylation of the WNK1 oncogene (which is overexpressed in colorectal cancer and is mainly involved in the regulation of metabolism) at the levels of 38.6 and 32.6% in the LoVo and SW620 cell lines, respectively." (PMID 36080216, 2022). "A similar targeting profile was observed for hsa-miR-192-5p: the canonical form bound EMT master-regulator ZEB2 and angiogenesis stimulator WNK1, while non-canonical 5′-isomiR regulated two other colorectal cancer oncogenes: NOX4 and MSN." (PMID 36275459, 2022).
non-small cell lung carcinoma (5 papers, 2017 to 2023). A group of at least three distinct histological types of lung cancer, including non-small cell squamous cell carcinoma, adenocarcinoma, and large cell carcinoma. "In conclusion, these data suggest that WNK1 is a novel molecule in SPARC-mediated mesenchymal signaling pathway in non-small cell lung cancer." (PMID 28969021, 2017). "Our study suggests that blockage of SPARC/WNK1/Snail signaling pathway could be a strategy to suppress migration of non-small cell lung cancer." (PMID 28969021, 2017).
Obesity (5 papers, 2020 to 2022). Accumulation of substantial excess body fat. "SLC24A3 and WNK1 are mapped to traits like fat body mass and body mass index which are closely associated with obesity." (PMID 32027667, 2020). "In the post-HCT group we found significantly lower expression of AGTR2, FLJ32810, NR3C2 and TMEM133 genes, and significantly higher expression of BAT2D1, MOV10, PIK3CG and WNK1 genes compared with the obesity control group." (PMID 33927307, 2021). "In the pre-HCT group we found significantly lower expression of AGTR2, BLK, FLJ32810 and TMEM133 genes, and significantly higher expression of MOV10 and WNK1 genes compared with the obesity control group." (PMID 33927307, 2021). "Among 8 unreported SSGs, the highly connected genes with obesity related genes is ENPEP followed by WNK1." (PMID 32027667, 2020). "Thus, WNK1, can act as one of the potential biomarker or targets for controlling obesity." (PMID 32027667, 2020). "Thus, the interaction between AKT3, WNK1 and SGK1 regulates adipogenesis in vivo, and dysregulation of this pathway can lead to increased adipogenesis and obesity as well as insulin resistance." (PMID 35880040, 2022).
Stroke (5 papers, 2017 to 2025). Sudden impairment of blood flow to a part of the brain due to occlusion or rupture of an artery to the brain. "Thus, by assessing expression at different levels in both males and females with all three causes of stroke, a more complete picture of WNK1 expression was obtained in this study." (PMID 33193047, 2020). "GWAS have linked two SNPs intronic to, or near, WNK1 with TG levels as well as stroke risk." (PMID 28178938, 2017). "rs880054 of WNK1 was significantly associated with SBP (p-value = 0.027), glyceride level (p-value = 0.026), weight (p-value = 0.024), IHD (p-value = 0.039), cerebrovascular accident (p-value = 0.02), and atrial fibrillation (p-value = 0.02)." (PMID 39859138, 2025). "At gene level, few were differentially expressed: ALDH2, ALOX5AP, F13A1, and IMPA2 (males, all stroke); ITGB3 (females, cardioembolic); ADD1 (males, atherosclerotic); F13A1, IMPA2 (males, lacunar); and WNK1 (females, lacunar)." (PMID 33193047, 2020). "Among them, Wnk1 and Tcerg1 were upregulated in DAM and might modulate the maturation of this stroke‐induced microglial subtype." (PMID 39930981, 2025).
hereditary spastic paraplegia (4 papers, 2016 to 2023). Hereditary spastic paraplegias (HSP) comprise a genetically and clinically heterogeneous group of neurodegenerative disorders characterized by progressive spasticity and hyperreflexia of the lower limbs. "Of note, there are nine genes among these targets that when mutated are known causes for inherited peripheral neuropathies (IPN) and hereditary spastic paraplegia (HSP) (Inf2, Sox10, Wnk1, Med25, Fa2h, Bscl2, Slc12a6, Kif1a and Kif5a)." (PMID 28077174, 2017).
neuropathy (4 papers, 2016 to 2025). A disorder affecting the nervous system that manifests with pain, tingling, numbness, and/or muscle weakness. "Also, a mutation on WNK1 is found to cause a type of neuropathy." (PMID 40943121, 2025). "WNK1 appears to play a regulatory role in autophagy by inhibiting the process, therefore truncating mutations in WNK1 leading to neuropathy might hinder its autophagy-related function and lead to toxic increase in autophagic flux that can have deleterious effects contributing to the neuropathology." (PMID 28553203, 2017).
schizophrenia (4 papers, 2015 to 2024). A major psychotic disorder characterized by abnormalities in the perception or expression of reality. "More recently, the over expression of WNK1 was reported to be associated with schizophrenia, a neurodevelopmental disorder." (PMID 27050411, 2016). "Within this gene set, the difference between AT-schizophrenia subjects and control pairs correlated either positively (WNK1) or negatively (SFRP2) with age." (PMID 38648100, 2024). "In support of this finding, WNK1 gene expression has been consistently reported to be up-regulated in the prefrontal cortex of schizophrenia sufferers in genome-wide expression profiling studies, thus providing support for a dysregulation of WNK1 in schizophrenia." (PMID 32714588, 2018).
hereditary sensory neuropathy (3 papers, 2014 to 2019). "Hereditary sensory and autonomic neuropathy (HSAN) type II with WNK1/HSN2 gene mutation is a rare disease characterized by early-onset demyelination sensory loss and skin ulceration." (PMID 27765018, 2016). "Additionally, a genetic disease known as hereditary sensory neuropathy (HSN) or hereditary sensory and autonomic neuropathy (HSAN) was initially believed to be caused by a mutation in a single exon open reading frame (ORF) located within intron 8 of the WNK1 allele, termed “HSN2”." (PMID 31165006, 2019).
Hyperglycemia (3 papers, 2015 to 2020). An increased concentration of glucose in the blood. "In the functional enrichment data, the gene WNK1 is reported in diseases like Diabetes Mellitus, Cardiovascular Diseases, Metabolic Syndrome X, Hyperglycemia and heart failure." (PMID 32027667, 2020). "We demonstrate a new perspective on the biological function of WNK1 in skeletal muscles beyond the regulation of ion transport and on the clues for the pathogenesis of hyperglycemia in T2D." (PMID 30410865, 2018). "Altogether, our results provide a new perspective on WNK1 function beyond the regulation of ion homeostasis and offer a new molecular aspect of insulin resistance and the consequent pathogenesis of hyperglycemia in T2D." (PMID 30410865, 2018). "Another hyperglycemia activated phospho-protein, WNK1, could regulate multiple signaling pathways related to cell proliferation, ion channel regulation and protein synthesis." (PMID 26337468, 2015).
leukemia (3 papers, 2020 to 2025). A malignant (clonal) hematologic disorder, involving hematopoietic stem cells and characterized by the presence of primitive or atypical myeloid or lymphoid cells in the bone marrow and the blood. "To further confirm the requirement of WNK1 signalling for mTORC1 activity, we generated MA9 leukaemia cells in which we knocked in a tag coding for mutant FKBP12 (FKBP12F36V) in both alleles of Wnk1." (PMID 40425534, 2025). "Treatment of these leukaemia cells with 4-hydroxytamoxifen (OHT) led to recombination of the Wnk1 locus and concomitant loss of WNK1 protein expression, confirming that WNK1 is essential for the proliferation of these leukaemia cells in vitro." (PMID 40425534, 2025). "Moreover, leukaemia cells expressing only the catalytically inactive WNK1 mutant showed a dramatic loss of proliferation, demonstrating the requirement for the catalytic activity of WNK1 to sustain AML proliferation." (PMID 40425534, 2025). "When the resulting FKBP12F36V-WNK1 leukaemia cells were treated with dTAG-13, WNK1 levels were undetectable within 1 h, accompanied by a significant decrease of S6K1 phosphorylation." (PMID 40425534, 2025). "To identify other potential targets, we performed mass spectrometry based quantitative phosphoproteomics analysis in Wnk1f/− leukaemia cells treated with 4-hydroxytamoxifen (OHT) for 48 h to knockout Wnk1, or with Compound 12 for 3 h to inhibit WNK1." (PMID 40425534, 2025). "Induced recombination of the Wnk1 locus resulted in increased survival for mice transplanted with Wnk1f/+, Wnk1f/− or Wnk1f/D368A leukaemia cells, though the effect for mice transplanted with Wnk1f/+ was less profound." (PMID 40425534, 2025). "Genetic disruption of Wnk1 strongly suppressed the growth of MA9 leukaemia cells to a degree comparable to targeting the essential gene Rps19." (PMID 40425534, 2025). "EdU labelling showed leukaemia cells with deletion of Wnk1 or leukaemia cells only expressing catalytically inactive WNK1 became apoptotic and exhibited a drastic reduction of cells in S-phase." (PMID 40425534, 2025). "Since T-ALL cells express high levels of MYC, which is essential for their proliferation, we hypothesize that WNK1 may contribute to the growth of T-ALL by maintaining high levels of MYC, making WNK1 a potential therapeutic target in this thymocyte-derived leukemia." (PMID 33051000, 2020). "Given these in vitro results and that Compound 12 is a selective WNK1 inhibitor, we tested its anti-leukaemia effects in vivo using a mouse MLL-AF9 leukaemia model." (PMID 40425534, 2025). "We show that genetic depletion and pharmacological inhibition of WNK1 or its downstream phosphorylation targets OXSR1 and STK39 strongly reduce cell proliferation and induce apoptosis in leukaemia cells in vitro and in vivo." (PMID 40425534, 2025). "Targeting WNK1 in all the human AML cell lines led to impaired growth, extending our results from the mouse MA9 leukaemia cells." (PMID 40425534, 2025). "OXSR1T185E,S325E, but not OXSR1WT or OXSR1D164A, maintained MA9 leukaemia cell proliferation in the absence of WNK1." (PMID 40425534, 2025). "In Wnk1f/− leukaemia cells, ectopic expression of either constitutively active human OXSR1T185E,S325E or human STK39T233E,S373E, maintained the phosphorylation of S6K1 and 4EBP1 upon OHT-induced Wnk1 deletion." (PMID 40425534, 2025). "To validate our initial observation, we cloned the two sgRNAs against Wnk1 giving the strongest dropout in the screen and transduced them individually in the Cas9-expressing MLL-AF9 driven mouse leukaemia cells (hereinafter referred to as MA9 leukaemia cells)." (PMID 40425534, 2025). "In support of this hypothesis, phosphorylated WNK1 was shown to block insulin-stimulated mitosis, and GDP366-induced phosphorylation of STMN1 promoted cell cycle arrest and apoptosis in leukemia cells." (PMID 37305581, 2023).
Sepsis (3 papers, 2022 to 2025). Sepsis is defined as life-threatening organ dysfunction caused by a dysregulated host response to infection. "They confirmed that CircMAPK1 exacerbates sepsis-induced lung injury by destabilizing KDM2B mRNA to suppress WNK1 expression, thus facilitating NLRP3-driven macrophage pyroptosis." (PMID 40458798, 2025). "Our findings demonstrated that the expression of WNK1 was downregulated in the blood samples of patients with sepsis, as well as in LPS/ATP-treated macrophages." (PMID 39300342, 2024). "In sepsis models, WNK1/TGF-β-activated kinase 1 (TAK1) axis suppresses LPS-induced inflammation and the activation of macrophages via NF-κB and MAPK signalings." (PMID 39300342, 2024). "CircMAPK1 exacerbates sepsis-induced lung injury by destabilizing KDM2B mRNA to suppress WNK1 expression, thus facilitating NLRP3-driven macrophage pyroptosis." (PMID 39300342, 2024). "To further understand the mechanism underlying circMAPK1/WNK1 axis in sepsis-induced lung injury, we first examined the expression of KDM2B and WNK1 in septic patients." (PMID 39300342, 2024). "KDM2B and WNK1 were markedly decreased in the blood samples of patients with sepsis-induced lung injury, compared with that of healthy volunteers." (PMID 39300342, 2024). "However, the specific role of KDM2B in potentially mediating the hypermethylation of WNK1 in sepsis-induced ALI remains an area for further investigation." (PMID 39300342, 2024). "However, the biological role of WNK1 in sepsis-induced lung injury remains elusive." (PMID 39300342, 2024). "Despite this known function, the specific mechanism of WNK1 in NLRP3-mediated macrophage pyroptosis and its role in sepsis-induced lung injury remains unelucidated." (PMID 39300342, 2024). "Our research adds to this understanding, showing that circMAPK1 was upregulated in sepsis patients and exacerbates lung injury, primarily regulated NLRP3-mediated macrophage pyroptosis via UPF1/KDM2B/WNK1/NLRP3 pathway." (PMID 39300342, 2024). "This study lies in its contribution to the nuanced understanding of the molecular interactions in sepsis, and circMAPK1/KDM2B/WNK1/NLRP3 axis was identified as a promising target for the targeted therapeutic strategy of sepsis-induced ALI." (PMID 39300342, 2024). "In conclusion, our findings illustrated that circMAPK1 promoted KDM2B mRNA decay via recruiting UPF1, thereby inhibiting KDM2B-mediated WNK1 demethylation to suppress WNK1 expression, and ultimately triggering NLRP3-mediated pyroptosis to exacerbate sepsis-induced lung injury." (PMID 39300342, 2024). "In summary, we hypothesized that circMAPK1 facilitated KDM2B mRNA decay via recruiting UPF1, and the inhibition of KDM2B-mediated WNK1 demethylation further suppressed WNK1 expression, thus triggering NLRP3-mediated pyroptosis in sepsis-induced ALI." (PMID 39300342, 2024). "There was a negative correlation between circMAPK1 and WNK1, as well as between circMAPK1 and KDM2B, while WNK1 positively correlated with KDM2B in patients with sepsis-induced lung injury." (PMID 39300342, 2024).
triple-negative breast carcinoma (3 papers, 2018 to 2023). An invasive breast carcinoma which is negative for expression of estrogen receptor (ER), progesterone receptor (PR), and human epidermal growth factor receptor 2 (HER2). "However, miR-93 interacts with WNK1 to inhibit the invasive potential of cancer cells in triple-negative breast cancer." (PMID 33535997, 2021).
Alzheimer disease (2 papers, 2013 to 2025). A progressive, neurodegenerative disease characterized by loss of function and death of nerve cells in several areas of the brain leading to loss of cognitive function such as memory and language. "Within the Red module in WM (6c), hub genes included those implicated in other neurological conditions and CNS functioning, including WNK1 (linked to both cardiovascular and Alzheimer’s disease) and NEO1 (involved in nervous system development and apoptosis)." (PMID 23406646, 2013).
bone cancer (2 papers, 2023). A primary or metastatic malignant neoplasm affecting the bone or articular cartilage. "In the serum of mice with bone cancer pain, the expression of WNK1 was significantly higher than that of normal mice (P < 0.01), and showed an upward trend with the passage of time." (PMID 37652923, 2023). "And WNK1 is involved in bone tumor pain formation, providing a corresponding target for the treatment of these diseases." (PMID 37980468, 2023). "Therefore, it is very important to accurately find the activation of WNK1 upstream and downstream target signal molecules under bone cancer pain stimulation, which is the focus of the next experimental research." (PMID 37652923, 2023). "Therefore, in this study, a new competitive Akt inhibitor of ATP, GSK690393, was used to block the Akt pathway to study the mechanism of PI3K/Akt/WNK1 in bone cancer pain." (PMID 37652923, 2023). "And the expression of WNK1 in bone cancer increased with time." (PMID 37652923, 2023). "The expression of PICs in the serum of mice with bone cancer pain was time-dependent and closely related to the expression of PI3K, Akt and WNK1 protein." (PMID 37652923, 2023).
cholangiocarcinoma (2 papers, 2022 to 2023). A carcinoma that arises from the intrahepatic biliary tree (intrahepatic cholangiocarcinoma) or from the junction, or adjacent to the junction, of the right and left hepatic ducts (hilar cholangiocarcinoma). "Additionally, UA treatment exerted anti-tumor effects in a rodent model by inhibiting the Akt/WNK1 signaling pathway and inducing autophagy in cholangiocarcinoma cells." (PMID 36673365, 2023).
chronic kidney disease (2 papers, 2018 to 2022). Impairment of the renal function secondary to chronic kidney damage persisting for three or more months. "We further illustrated that WNK1 protein abundance in skeletal muscle was increased by chronic voluntary wheel running exercise (hypertrophic stimulus) and markedly decreased by adenine-induced chronic kidney disease (atrophic stimulus) in mice." (PMID 29904119, 2018).
COVID-19 (2 papers, 2024). A disease caused by infection with severe acute respiratory syndrome coronavirus 2. "Our findings thus suggest a potential mechanism for COVID-19-mediated cardiac pathology and recommend the application of WNK1 inhibitor for therapy especially in individuals with post-acute sequelae of COVID-19." (PMID 39102426, 2024). "Of note, WNK1 exhibited significantly reduced phosphorylation on multiple sites, including the activation loop S1261 residue, suggesting that WNK1 activity is inhibited in the COVID-19 patients." (PMID 38389037, 2024). "As an important regulator of electrolyte homeostasis, WNK1 may play a role in regulating blood pressure in COVID-19 patients." (PMID 38389037, 2024).
endometrial cancer (2 papers, 2020 to 2025). Primary or metastatic malignant neoplasm involving the endometrium (mucous membrane that lines the endometrial cavity). "Although we demonstrate here that WNK1 positively regulated PP2A activity and propose a possibility that WNK1 could be associated with endometrial cancer, its exact role in endometrial cancer is yet unknown and worth exploring." (PMID 33048843, 2020). "Nonetheless, investigating the activity of WNK1 in human endometrial cancers would shed light on its potential role in this disease." (PMID 33048843, 2020). "Furthermore, the effects of PPP2R1A overexpression in GC cells differ from its role in promoting the proliferation of ovarian and endometrial cancer cells, as does its ability to inhibit WNK1-induced cell migration in liver cancer cells." (PMID 40251453, 2025).
gastrointestinal stromal tumor (2 papers, 2021 to 2022). "Mutations of PPP2R1A promote cells proliferation by upregulating the phosphorylation levels of Akt, ERK, and WNK1 in gastrointestinal stromal tumors and by interactions with the PP2A inhibitor TIPRL1 in uterine cancer." (PMID 34076143, 2021). "PPP2R1A, the subunit of PP2A, has been reported to dephosphorylate and inactivate WNK1, while mutant PPP2R1A increases pWNK in gastrointestinal stromal tumors." (PMID 36292952, 2022).